SOS1 (SOS Ras/Rac guanine nucleotide exchange factor 1)
Diseases named in the same sentence as SOS1 in open-access papers (continued):
Sharing a sentence is not in itself a finding about the gene and the disease.
lung carcinoma (7 papers, 2017 to 2024). "This study aimed to elucidate the underlying mechanism involving the DNMT1/miR-152-3p/SOS1 axis in regulating the self-renewal and tumor growth of LCSLCs (lung cancer stem-like cells)." (PMID 38622665, 2024). "The demonstration of the in vivo effect of this PROTAC is promising for lung cancer patients with KRAS mutations, as chemicals targeting SOS1-based therapy are currently the subject of ongoing clinical trials." (PMID 36678835, 2023). "In silico analyses of human lung cancer databases support also the dominant role of SOS1 regarding tumor development and survival in LUAD patients." (PMID 37730692, 2023). "Another regulator of oncogenic progression in lung cancer is son of sevenless homolog 1 (SOS1)." (PMID 36678835, 2023). "Indeed, future studies of acute SOS1 pharmacologic inhibition in the mouse may help characterizing potentially evolving changes occurring in the lung cancer TME over time." (PMID 37730692, 2023). "Our analysis of collected lung cancer specimens revealed elevated expression levels of DNMT1, CD44, and SOS1 in certain NSCLC tissues, establishing a positive correlation between DNMT1 and SOS1 in the progression of NSCLC." (PMID 38622665, 2024).
melanoma (7 papers, 2016 to 2022). A malignant, usually aggressive tumor composed of atypical, neoplastic melanocytes. "Moreover, upregulated levels of circulating RNA for Sos1 have been detected in the plasma of melanoma patients, and a recent report has also demonstrated that enhanced expression of Sos1 is predictive of poor prognosis in uveal malignant melanoma patients." (PMID 33946974, 2021). "Finally, genetically mediated abrogation of Sos1 in human melanoma cell lines strongly reduces the migratory ability of these tumor cells." (PMID 33946974, 2021). "Altogether, these data suggest the existence of a feedback loop upon metabolic stress in NRASQ61mutant melanomas between the RAS pathway and the glycolytic route, connecting BRAF, PFKFB2, PFK1, SOS1/2 and NRAS." (PMID 36402789, 2022). "We measured levels of SOS1, ATM1, CD109, and AMFR mRNA fragments in plasma samples from 173 melanoma patients and 47 healthy controls." (PMID 30634628, 2019). "Levels of ATM, AMFR, CD109, and SOS1 were all significantly higher (p < 0.001) in plasma samples from either stage 0, stage I/II, or stage III/IV melanoma patients than in healthy controls (respectively), consistent with the NGS data (Table A1)." (PMID 30634628, 2019). "Levels of ATM1, AMFR, SOS1, and CD109 gene fragments were up-regulated (p < 0.001) in melanoma samples (n = 144) compared to healthy controls (n = 41) (AUC = 0.825)." (PMID 30634628, 2019).
atrial septal defect (5 papers, 2011 to 2025). Interauricular communication is a congenital malformation characterized by a communication between the atrial chambers of the heart. "PTPN11 variants were linked to PS and atrial septal defects, SOS1 to multiple cardiopathies, and RAF1 to HCM." (PMID 40332000, 2025). "Finally, mutation analysis performed on cohorts of individuals with nonsyndromic pulmonic stenosis, atrial septal defects, and ventricular septal defects excluded a major contribution of germline SOS1 lesions to the isolated occurrence of these cardiac anomalies." (PMID 21387466, 2011). "For example, in the case of atrial septal defect (ASD) and ventricular septal defect (VSD), candidate genes can be counted: NKX2-5, GATA4, TBX20, MYH6, and TBX5, while the pathogenesis of atrioventricular septal defect (AVSD) involves genes, such as PTPN11, KRAS, SOS1, RAF1, and CRELD1." (PMID 34946970, 2021).
gastric cancer (5 papers, 2018 to 2024). A primary or metastatic malignant neoplasm involving the stomach. "Next, we performed a loss-of-function assay to investigate whether SOS1 plays an essential role in the oncogenic effects of USP22 on gastric cancer cells." (PMID 32063746, 2020). "Knockdown of RAS activator son of sevenless 1 (SOS1) was performed to investigate the role of SOS1 in USP22-regulated gastric cancer cell behavior and RAS signaling both in vitro and in vivo." (PMID 32063746, 2020). "USP22 overexpression in gastric cancer cells induces the upregulation of SOS1 and activation of the RAS/ERK and PI3K/AKT pathways." (PMID 32063746, 2020). "We do acknowledge that RUNX transcription factors have diverse targets in vivo and they potentially have multiple other targets than SOS1-ErbB2/HER2 in the gastric cancer cells." (PMID 29686309, 2018). "Taken together, these data collectively suggested that RUNX1 positively regulates the ErbB2/HER2 signaling pathway through directly transactivating SOS1 expression in the gastric cancer cells." (PMID 29686309, 2018). "Intriguingly, we found that SOS1 protein was also highly-expressed in the gastric cancer cell lines relative to the normal gastric tissue." (PMID 29686309, 2018). "We herein revealed that RUNX1 potentially participates in the maintenance of gastric cancer cells through enhancing the activity of the ErbB2/HER2 signaling pathway by directly transactivating SOS1 expression." (PMID 29686309, 2018). "Together with the results obtained in the RUNX1 knockdown experiments, we were convinced that RUNX1 controls the ErbB2/HER2 signaling cascade through modulating SOS1 expression in gastric cancer cells." (PMID 29686309, 2018). "Herein we report that RUNX1 regulates the ErbB2/HER2 signaling pathway in gastric cancer cells through transactivating SOS1 expression, rendering itself an ideal target in anti-tumor strategy toward this cancer." (PMID 29686309, 2018). "For this purpose, we prepared shRNAs specifically targeting SOS1 and examined their effects on the maintenance of gastric cancer cells." (PMID 29686309, 2018). "The oncogenic role of USP22 in gastric cancer relies on SOS1 expression." (PMID 32063746, 2020). "Although previous studies have identified many genetic alterations, epigenetic modifications, and environmental factors that are responsible for hyperactive RAS in cancer, the role of SOS1/RAS signaling in gastric cancer remains unknown." (PMID 32063746, 2020). "Our findings identify the USP22/SOS1/RAS axis as a promising therapeutic target in gastric cancer." (PMID 32063746, 2020). "Targeting the USP22/SOS1/RAS axis represents a promising strategy in gastric cancer therapy." (PMID 32063746, 2020). "In this study, the results of a ChIP assay allowed us to demonstrate for the first time that USP22 may interact with RAS activator SOS1 in gastric cancer." (PMID 32063746, 2020). "To investigate whether SOS1 plays an essential role in mediating the tumorigenic roles of USP22 in gastric cancer, we silenced its expression in USP22-overexpressing SGC7901 cells." (PMID 32063746, 2020). "Although SOS family proteins have been shown to take pivotal roles in the RTKs signaling cascades and higher expressions of SOS1 in solid tumors relative to their normal counterpart tissues have been repeatedly reported, its role in gastric cancer cells has remained elusive so far." (PMID 29686309, 2018). "We thus investigated the oncogenic role of SOS1 in gastric cancer cells." (PMID 29686309, 2018). "Furthermore, SOS1 silencing could reverse the effects of USP22 on gastric cancer cell behavior and RAS signaling both in vitro and in vivo." (PMID 32063746, 2020). "Our findings identify the USP22/SOS1/RAS axis as a novel and promising therapeutic target in gastric cancer." (PMID 32063746, 2020).
gastric cancer (continued). "Our results suggest that USP22 acts as an oncogene in gastric cancer in a SOS1-dependent manner, identifying the USP22/SOS1/RAS axis as a potential therapeutic target in gastric cancer." (PMID 32063746, 2020). "Knockdown of RUNX1 led to the decreased expression of SOS1 as well as dephosphorylation of ErbB2/HER2, subsequently suppressed the proliferation of gastric cancer cells." (PMID 29686309, 2018). "Together with our finding that HER2-depletion indeed decelerates the growth rate of MKN45 cells, these data collectively underpin the importance of SOS1 expression in the ErbB2/HER2 signaling cascade and in the maintenance of gastric cancer cell lines." (PMID 29686309, 2018). "Furthermore, SOS1 upregulation in USP22-overexrpessing gastric cancer cells and xenograft tumor tissue is accompanied by activation of the RAS/ERK and RAS/PI3K/AKT pathways, which is attenuated by SOS1 silencing." (PMID 32063746, 2020). "Furthermore, our study indicated that SOS1 was upregulated in USP22-overexpressing gastric cancer cells and xenograft tumor tissue, accompanied by activation of the RAS/ERK and PI3K/AKT pathways, suggesting that SOS1/RAS signaling mediates the oncogenic role of USP22 in gastric cancer." (PMID 32063746, 2020).
LEOPARD syndrome (5 papers, 2011 to 2024). "Seven genes (PTPN11, SOS1,KRAS, RAF1, BRAF,SHOC2 and MEK1, alias MAP2K1) have beencausally related to NS and closely related conditions (including LEOPARDsyndrome) and clinically related disorders (e.g. neurofibromatosis type 1)." (PMID 21526175, 2011). "No mutations onthe RAF1 gene were identified in negative cases ofPTPN11, SOS1, and KRAS.Patients #39 and #41 were posteriorly diagnosed with suffering from LEOPARDsyndrome, and in fact, they carried the characteristic mutations on genesPTPN11." (PMID 21526175, 2011).
leukemia (5 papers, 2021 to 2025). A malignant (clonal) hematologic disorder, involving hematopoietic stem cells and characterized by the presence of primitive or atypical myeloid or lymphoid cells in the bone marrow and the blood. "In summary, this study suggests that PROTAC-mediated SOS1 degradation represents an effective therapeutic strategy for treating not only KRAS-mutant cancers but also BCR–ABL–harboring leukemia." (PMID 39437162, 2025). "In particular, a specific, critical requirement of SOS1 was demonstrated for development of BCR–ABL-driven leukemia, as well as in skin homeostasis and chemically induced carcinogenesis." (PMID 34205562, 2021). "In our previous research, SOS1 was a direct target gene of mir-181a, which was a prognostic marker in leukemia." (PMID 34938856, 2021). "Thus, we evaluated the expression of SOS1 in leukemia cells and patient samples at both the mRNA and protein levels, which was found to be higher than that in normal human samples." (PMID 34938856, 2021). "Our findings suggest that SOS1 PROTACs may potentially serve as a valuable option for exploring the biological functions of SOS1 and as a basis for developing novel antitumor drugs targeting KRAS-mutant cancers and BCR–ABL–driven leukemia." (PMID 39437162, 2025).
Obesity (5 papers, 2015 to 2024). Accumulation of substantial excess body fat. "Following previous work, SOS1 was post-transcriptionally regulated by miR-483 and promoted BC metastasis by obesity-activated c-Met signaling." (PMID 37626035, 2023).
Chylothorax (4 papers, 2022 to 2024). The presence of chyle in the thoracic cavity. "Postnatally, the prevalence of lymphedema differs from 16% in patients with pathogenic PTPN11 variants to 44% in patients with pathogenic SOS1 variants, and the prevalence of acquired chylothorax is 4% in patients with pathogenic RIT1 variants." (PMID 39229301, 2024). "For example, both germline and somatic inactivating mutations affecting H-Ras, N-Ras, K-Ras, and Son of sevenless homolog 1 (SOS1) have been linked to development of chylothorax and chylous ascites." (PMID 38201272, 2023).
glioblastoma (4 papers, 2020 to 2025). The most malignant astrocytic tumor (WHO grade IV). "Although our study focused on NF1 loss leading to Ras activation, RTKs, such as PDGFRA and EGFR, which are recurrently mutated in glioblastoma, can also activate Ras signaling through Ras GEFs such as SOS1." (PMID 40985888, 2025).
pulmonary stenosis (4 papers, 2011 to 2025). "Four of five SOS1 cases had exon 10 variants, with consistent short stature, ptosis, and pulmonary stenosis, reaffirming known genotype–phenotype correlations." (PMID 41292581, 2025). "SOS1 was also significantly associated with pulmonary stenosis in our cohort, which has been reported in Korean patients in the past." (PMID 41292581, 2025). "Similarly, four of five SOS1 cases harbored exon 10 variants with consistent short stature, ptosis, and pulmonary stenosis, reaffirming established associations." (PMID 41292581, 2025). "A trend was observed for the association between PTPN11 and SOS1 variants and pulmonary stenosis, though not statistically significant due to the small cohort size." (PMID 41292581, 2025).
viral infection (4 papers, 2014 to 2017). "Although the exact mechanism remains unclear between the activation of SOS1 and virus infection, it indicates that EV71 infection activates SOS1 gene, which may enhance the activation of Ras/Raf/MEK signaling cascade in EV71-infected iDCs." (PMID 25548009, 2014).
bladder cancer (3 papers, 2022 to 2025). "On the other hand, miR-124-3p was stated as a suppressor of tumors in prostate and bladder cancer and was identified as a target of the SOS1 gene." (PMID 36140796, 2022). "DLEU2 facilitates bladder cancer progression through miR-103a-2-5p/SOS1 axis." (PMID 40226549, 2025).
chronic myeloid leukemia (3 papers, 2021 to 2025). "The depletion of SOS1 markedly inhibits cell growth either in vitro or in vivo and significantly increases the sensitivity of chronic myeloid leukemia cells to imatinib." (PMID 34938856, 2021). "BAY-293, an inhibitor of SOS1/Ras, was found to depress proliferation and colony formation in chronic myeloid leukemia cells with resistance and BCR-ABL independence." (PMID 34938856, 2021). "HPLC assay confirms that intracellular accumulation of imatinib is accompanied by upregulation of SLC22A4 through SOS1 inhibition in both sensitive and resistant chronic myeloid leukemia cells." (PMID 34938856, 2021). "The PROTAC SIAIS562055 sustainably degrades SOS1 and inhibits downstream ERK signaling, showing strong antiproliferative activity and synergistic effects with KRAS inhibitors in KRAS-mutant cancers and BCR–ABL inhibitors in chronic myeloid leukemia." (PMID 39437162, 2025). "Significance: The PROTAC SIAIS562055 sustainably degrades SOS1 and inhibits downstream ERK signaling, showing strong antiproliferative activity and synergistic effects with KRAS inhibitors in KRAS-mutant cancers and BCR–ABL inhibitors in chronic myeloid leukemia." (PMID 39437162, 2025). "Despite this, small-molecule inhibitors targeting SOS1 have shown limited efficacy in clinical trials for KRAS-mutant cancers, and their potential as a therapeutic approach for chronic myeloid leukemia (CML) remains largely unexplored." (PMID 39437162, 2025). "Furthermore, LC-MS/MS and RNA-seq assays reveal that SOS1 negatively regulates the expression of SLC22A4, a member of the carnitine/organic cation transporter family, which mediates the active uptake of imatinib into chronic myeloid leukemia cells." (PMID 34938856, 2021). "Regarding tumoral pathogenesis, our earlier studies of SOS1- and/or SOS2-knockout mice also suggested the critical contribution/participation of SOS1 in the development of RAS-dependent, DMBA/TPA chemically induced skin tumors and Bcr/Abl-driven chronic myeloid leukemia (CML)." (PMID 36010887, 2022).
colon cancer (3 papers, 2018 to 2022). "PEITC inhibited the invasion and migration of human colon cancer HT29 cells by decreasing SOS-1, PKC, ERK1/2, and Rho A which led to the reduction of MMP-2 and MMP-9." (PMID 35368876, 2022). "Invasion and migration of colon cancer was prevented by the inhibition of genes involved in the cell cycle such as the son of sevenless homolog 1 (SOS-1), PKC, ERK1/2 and Ras homolog gene family, member A (Rho A)." (PMID 30445746, 2018).
diabetes (3 papers, 2003 to 2023). "We examined 35 genes predicted to have their major influence on insulin action, and three (9%)—INSR, PIK3R1, and SOS1—showed significant associations with diabetes." (PMID 14551916, 2003). "For DM patients, SOS1 was statistically significantly associated with gestational diabetes mellitus risk at the gene level." (PMID 36923118, 2023).
glioma (3 papers, 2017 to 2019). A benign or malignant brain and spinal cord tumor that arises from glial cells (astrocytes, oligodendrocytes, ependymal cells). "For example, miR-124 could inhibit the growth of glioblastoma by downregulating SOS1, radio-sensitizing human glioma cells by targeting CDK4, and suppressing the migration and invasion of glioma cells via Capn4 and ROCK1." (PMID 31052326, 2019). "Interestingly, miR-124 inhibited the migration and invasion of glioma cells through down-regulation of ROCK1, SOS1, CDK4, STAT3, and PPP1R13L expression, indicating miR-124 may be a valuable biomarker for glioma." (PMID 28060761, 2017).
plexiform neurofibroma (3 papers, 2019 to 2025). An elongated and multinodular neurofibroma, formed when the tumor involves either multiple trunks of a plexus or multiple fascicles of a large nerve, such as the sciatic. "Another case report described spinal lesions resembling plexiform neurofibromas in NS caused by a variation in the SOS1 gene." (PMID 40507736, 2025). "Moreover, three negative patients had a spinal form of NF1 and recently Santoro has reported p.Ser548Arg missense pathogenic variant in SOS1 gene in a patient with bilateral cervical and lumbar spinal lesions resembling plexiform neurofibromas and features suggestive of NF1." (PMID 32575496, 2020). "In addition, a SOS1 mutation was identified in two familial cases with previous clinical diagnosis of NF1 and multiple spinal nerve enlargements resembling plexiform neurofibromas." (PMID 32575496, 2020).
thyroid cancer (3 papers, 2021 to 2025). "This interaction regulated the expression of proteins such as SOS1, c-myc, and CCND1, consequently inhibiting abnormal proliferation of thyroid cancer cells." (PMID 37470034, 2023). "In conclusion, this study demonstrated that KRAS/SOS-1 inhibition could be a promising therapeutic target for the treatment of ATC and highlighted BAY-293 as an innovative molecule that needs further research to fully evaluate its efficacy in the field of thyroid cancer." (PMID 40141222, 2025).
autoimmune disease (2 papers, 2021). A disorder resulting from loss of function or tissue destruction of an organ or multiple organs, arising from humoral or cellular immune responses of the individual to their own tissue constituents. "In no case an autoimmune disorder was diagnosed, except for one case of psoriasis in a patient (1/69, 1.45%) with SOS1 mutation." (PMID 34600590, 2021).
Costello syndrome (2 papers, 2020 to 2023). "The remaining genes involved were RAF1 (three patients, all with Costello syndrome suspicion), RIT1 (two patients), BRAF (one patient), MAP2K1 (three patients), MAP2K2 (two patients), PTPN11 (two patients), SOS1 (one patient), and SHOC2 (three patients, two of them with Costello syndrome suspicion)." (PMID 37568403, 2023).
developmental delay (2 papers, 2023 to 2025). "A postnatally described central nervous system anomaly in the presence of the SOS1 gene variation was a corpus callosum agenesis with severe developmental delay." (PMID 40507736, 2025).
gestational diabetes mellitus (2 papers, 2019 to 2023). "Polymorphism in SOS1 is responsible for the progression of gestational diabetes mellitus, but this polymorphic gene may link with insulin resistance and NIDDM." (PMID 30678306, 2019).
growth disorder (2 papers, 2013 to 2016). "However, SNPs in two genes, IGFBP3 and SOS1, were common to both conditions, and these genes may have an impact on r-hGH sensitivity independent of the etiology of the growth disorder." (PMID 23761422, 2013).